GNPTAB (N-acetylglucosamine-1-phosphate transferase subunits alpha and beta)
Description:
Catalyzes the formation of mannose 6-phosphate (M6P) markers on high mannose type oligosaccharides in the Golgi apparatus. M6P residues are required to bind to the M6P receptors (MPR), which mediate the vesicular transport of lysosomal enzymes to the endosomal/prelysosomal compartment.
Synonyms: GNPTA; KIAA1208; MGC4170; ICD
Tractability: Small molecule: a structure with a bound ligand is known. Antibody: UniProt predicts a signal peptide or a membrane-spanning region. PROTAC: ubiquitination databases record sites on it; its protein half-life has been measured.
Gene: Protein-coding gene on chromosome 12 (101,745,486 to 101,830,980, reverse strand). Ensembl gene ENSG00000111670.
Subcellular location: Golgi apparatus membrane (N-acetylglucosamine-1-phosphotransferase subunit alpha); Golgi apparatus membrane (N-acetylglucosamine-1-phosphotransferase subunit beta)
Subcellular location (Human Protein Atlas): Golgi apparatus
Gene Ontology:
Molecular function: protein binding; UDP-N-acetylglucosamine-lysosomal-enzyme N-acetylglucosaminephosphotransferase activity; calcium ion binding; transferase activity, transferring phosphorus-containing groups
Biological process: carbohydrate phosphorylation; lysosome organization; N-glycan processing to lysosome; protein transport
Cellular component: Golgi apparatus; Golgi membrane
Genetic constraint (gnomAD): Loss-of-function variants: 63 observed, 97.11 expected, observed/expected ratio (o/e) 0.65, 90% interval 0.53 to 0.8. The upper end of that interval is the gene's LOEUF score, 0.8, which puts it in group 3 of 6, group 1 being the genes least tolerant of losing a copy. Missense variants: 1,077 observed, 1,277.8 expected, observed/expected ratio (o/e) 0.84, 90% interval 0.8 to 0.89. Synonymous variants: 430 observed, 469.25 expected, observed/expected ratio (o/e) 0.92, 90% interval 0.85 to 0.99.
Gene-disease validity (ClinGen):
ClinGen rates the evidence that GNPTAB causes each of these diseases.
GNPTAB-mucolipidosis (autosomal recessive): Definitive. An autosomal recessive mucolipidosis disorder caused by bi-allelic variants in the GNPTAB gene.
Homologues: Orthologues: chimpanzee GNPTAB (99% identical), macaque GNPTAB (98% identical), dog GNPTAB (91% identical), rabbit GNPTAB (90% identical), mouse Gnptab (86% identical), pig GNPTAB (86% identical), rat Gnptab (85% identical), guinea pig GNPTAB (76% identical), tropical clawed frog gnptab (66% identical), zebrafish gnptab (63% identical), Drosophila melanogaster Gnptab (19% identical), Caenorhabditis elegans C05D12.3 (14% identical), and 1 more.
Diseases named in the same sentence as GNPTAB in open-access papers:
GNPTAB is named in the same sentence as 40 diseases in open-access papers, as found by Europe PMC text mining. Sharing a sentence is not in itself a finding about the gene and the disease. The quoted sentences say what the papers report.
mucolipidosis II (22 papers, 2013 to 2025). "In mucolipidosis II (also called I-cell disease), which is caused by biallelic pathogenic variants of the GNPTAB gene, transport of major lysosomal hydrolases to lysosomes is impaired." (PMID 38354786, 2024). "In fact, a homozygous variant c.3503_3504del (p.Leu1168Glnfs*5) in the GNPTAB gene was observed which led to the genetic diagnosis of Mucolipidosis II/III." (PMID 38730490, 2024). "Mucolipidosis II alpha/beta is caused by variants in the GNPTAB gene, which encodes the α/β-precursor of GlcNAc-1-phosphotransferase." (PMID 37484777, 2023). "Mucolipidosis II (ML II; I-cell disease) is caused by a deficiency of N-acetylglucosamine-1-phosphotransferase (GNPTAB; EC 2.7.8.17), which leads to a failure to internalize acid hydrolases into lysosomes for proper catabolism of various substances." (PMID 30591066, 2018). "The fetuses carried the same GNPTAB mutations as the mucolipidosis II/III probands in the prenatal diagnosis." (PMID 28095893, 2017). "These genes are associated with skeletal dysplasias, including progressive pseudorheumatoid dysplasia (WISP3), Joubert syndrome and ciliopathies (CSPP1), mucolipidosis types II/III (GNPTAB), and Larsen syndrome or other spondyloepiphyseal dysplasias (FLNB)." (PMID 40428312, 2025). "An example of such a disorder is Mucolipidosis type II (MLII), a rare inherited condition caused by mutations in the GNPTAB gene." (PMID 40747612, 2025). "Mutations in genes working in the M6P pathway underlie genetic disorders such as Mucolipidosis type II (MLII), which is caused by mutations in GNPTAB." (PMID 40747612, 2025). "Mucolipidosis type II (MLII), or I-cell disease, is a lysosomal storage disease (LSD) caused by variants in the GNPTAB gene on chromosome 12q23.2 and generally results in death before the age of 10 years." (PMID 37484777, 2023). "Mucolipidosis type II (MLII), or I-cell disease, is a rare lysosomal storage disease (LSD) caused by variants in the GNPTAB gene." (PMID 37484777, 2023). "Mucolipidosis type II (MLII; MIM #252500), the most severe form of the disease, is caused by mutations in the GNPTAB gene encoding the membrane-bound precursor of α- and β-subunits of GlcNAc-1-phosphotransferase (EC 2.7.8.17)." (PMID 33023972, 2020). "Mucolipidosis II and III alpha/beta are autosomal recessive diseases caused by mutations in the GNPTAB gene which encodes the α and β subunits of the N-acetylglucosamine-1-phosphotransferase." (PMID 27662472, 2016). "Mucolipidosis II/III are diseases caused by a knockout or abnormities in the N-acetylglucosamine-1-phosphate transferase alpha and beta subunits (GNPTAB) gene." (PMID 28101008, 2016). "In this study, an elevated level of Globotriaosylsphingosine (Lyso-Gb3), an already known biomarker for Fabry disease, was confirmed in the knock-out cells of the GLA, GNPTAB, and PSAP genes and models for Fabry, mucolipidosis II/III (ML II/III), and combined saposin deficiency, respectively." (PMID 40650054, 2025). "Indeed, triclabendazole reduced the transduced GAG core proteins in the MPS model cells, including IDUA KO cells, ARSB KO cells, and GUSB KO cells, as well as in GNPTAB KO cells, a model cell for mucolipidosis type II." (PMID 40822349, 2025). "GNPTAB is involved in mucolipidosis II and III, two lysosomal disorders with neurologic symptoms, and harmful variants in GNPTAB have been identified both as a risk factor for the development of Parkinson’s disease and as enhancers of α-synuclein neurotoxicity in Drosophila." (PMID 39766783, 2024). "Mucolipidosis II (ML II, OMIM 252500) is a hereditary lysosomal storage disease caused by the deficiency of N-acetylglucosamine-1-Phosphotransferase (GNPTAB, EC 2.7.8.17, previously known as GNPTA)." (PMID 30591066, 2018). "Mutations in GNPTAB and GNPTG genes could cause mucolipidosis types II and III, which are severe forms of autosomal recessive lysosomal storage diseases." (PMID 25643770, 2015).
mucolipidosis II (continued). "Mucolipidosis II/III (OMIM 252500, 252600 and 252605) is caused by a lack of active enzyme GlcNAc-1-phosphotransferase (GNPTAB, GNPTG, EC 2.7.8.17), which is involved in the phosphorylation step in the synthesis of the mannose 6-phosphate marker present on the lysosomal membrane." (PMID 33669444, 2021). "Besides, mucolipidosis II (Gnptabc.3082insC) mice (which lack GNPTAB) do not exhibit lack of endochondral bone formation or Col II entrapment in the ER." (PMID 25147951, 2014).
lysosomal storage disease (6 papers, 2015 to 2025). A metabolic disorder caused by mutations in proteins critical for lysosomal function, including lysosomal enzymes, lysosomal integral membrane proteins, and proteins involved in the post-translational modification and trafficking of lysosomal proteins. "Mutations in GNPTAB that cause a complete loss of GlcNAc-1-phosphotransferase activity underlie the lysosomal storage disorder mucolipidosis II (also called I-cell disease)." (PMID 40332073, 2025). "Mutations in GNPTAB underlie mucolipidosis II and mucolipidosis III α/β, which are inherited lysosomal storage disorders caused by a defective UDP-N-acetylglucosamine:lysosomal-enzyme N-acetylglucosamine phosphotransferase." (PMID 40332073, 2025).
mucolipidosis (6 papers, 2015 to 2022). A group of inherited lysosomal storage diseases characterized by accumulation of lipids and carbohydrates in the tissues, resulting in mental disabilities and skeletal malformations. "Variants of GNPTAB are associated with the LSD mucolipidosis." (PMID 30655525, 2019). "Mucolipidosis alpha/beta is an inborn error of metabolism characterized by deficiency of GlcNAc-1-phosphotransferase, in which essential alpha/beta subunits are encoded by the GNPTAB gene." (PMID 30208878, 2018). "Mucolipidosis (ML) II (OMIM 252500) and ML III (OMIM 252600) alpha/beta are lysosomal storage diseases (LSDs) caused by variants in the GNPTAB gene located on chromosome 12q23.2." (PMID 35463894, 2022). "To further understand the relationship between GNPTAB dysfunction and EBOV infection, we tested fibroblasts from six patients with MLIII, a less severe form of mucolipidosis, usually characterized by a residual level of GlcNAc-phosphotransferase activity." (PMID 30655525, 2019). "While GNPTAB deficiency is associated with mucolipidosis, the clinical manifestations occur much more slowly than the acute course of EBOV infection, and the risks of short-term GNPTAB inhibition may be outweighed by the benefits for a disease with a high case fatality rate." (PMID 30655525, 2019).
pseudo-Hurler polydystrophy (3 papers, 2013 to 2024). "In addition, both affected individuals in family 2 were carriers of a known pathogenic variant in an additionallysosomal disease gene, GNPTAB (for mucolipidosis III)." (PMID 39766783, 2024). "Mucolipidosis type III alpha/beta (MLIII alpha/beta), also called pseudo-Hurler polydystrophy, is associated with GNPTAB variants that retain some residual GlcNAc-phosphotransferase activity." (PMID 30655525, 2019).
dyslexia (2 papers, 2015 to 2020). A learning disorder characterized by an impairment in processing written words. "Although the core SNP was associated with dyslexia of Chinese characters, GNPTAB has been found to be related to stuttering." (PMID 32560373, 2020). "As previous study reported association of GNPTAB, GNPTG and NAGPA with stuttering, we investigated these genes with dyslexia through association analysis." (PMID 25643770, 2015).
fronto-temporal dementia (1 paper, 2020). "In other neurodegenerative diseases, there is the strong association of heterozygous variants of PGN, the progranulin gene with fronto-temporal dementia and variants of GNPTAB, GNPTG, and the functionally related NAGPA gene with non-syndromic stuttering." (PMID 33005626, 2020).
language disorder (1 paper, 2015). A category of disorders characterized by an impairment in the development of an individual's language capabilities, which is in contrast to his/her non-verbal intellect. "Therefore, the three genes (GNPTAB, GNPTG and NAGPA) that may predispose people to stuttering are potential candidate risk genes for other speech and language disorders." (PMID 25643770, 2015).
melanoma (1 paper, 2024). A malignant, usually aggressive tumor composed of atypical, neoplastic melanocytes. "Taken together, our results revealed the association of lysosome function to melanoma metastasis via the GNPTAB, IGF2R, and TFEB axis." (PMID 38750105, 2024). "We observed in WM1716 melanoma cell line, that neither, nIGF2R or GNPTAB inhibition, interfered with autophagy markers, although in those conditions invasiveness potential was reduced." (PMID 38750105, 2024). "Indeed, GNPTAB depletion by siRNAs, phenocopied the depletion of IGF2R and reduced melanoma invasiveness potential." (PMID 38750105, 2024).
osteoporosis (1 paper, 2021). A condition of reduced bone mass, with decreased cortical thickness and a decrease in the number and size of the trabeculae of cancellous bone (but normal chemical composition), resulting in increased fracture incidence. "XPR1, SLC4A2, and GNPTAB were previously reported to be related to osteoporosis, but GRAMD1B, ITGA6, and DUSP6 have never been studied with respect to any musculoskeletal-related diseases." (PMID 34475393, 2021).
speech disorder (1 paper, 2025). A term referring to disorders characterized by the disruption of normal speech. "Mutations in NAGPA, GNPTG, and GNPTAB have been associated with the speech disorder in Pakistani family members." (PMID 39857822, 2025).
stuttering disorder (1 paper, 2023). "It has been reported that point mutations in highly conserved locations in GNPTAB, GNPTG, and NAGPA genes were linked to stuttering disorders." (PMID 38020803, 2023). "It has been shown that specific point mutations in four genes that are involved in the lysosomal enzyme-targeting pathway (i.e., GNPTAB, GNPTG, NAGPA, and AP4E1) are linked to stuttering disorder, in which they may contribute to up to 20% of the cases (Frigerio;Domingues and Drayna, 2017)." (PMID 38020803, 2023).
cancer (3 papers, 2018 to 2024). A tumor composed of atypical neoplastic, often pleomorphic cells that invade other tissues. "Also chosen were two randomly selected ARA-lincRNAs that are neighbors of C1orf174 and GNPTAB, which have not been related to any cancer, however, they encode proteins that are shown at The Human Protein Atlas3 as being possible prognostic markers of a number of cancers." (PMID 29875794, 2018).
autosomal recessive disease (1 paper, 2023). Autosomal recessive form of disease. "Mucolipidosis II and III (MLII and MLIII) are autosomal recessive diseases caused by pathogenic variants in GNPTAB and GNPTG genes that lead to defects in GlcNAc-1-phosphotransferase." (PMID 38047750, 2023).
skeletal dysplasia (1 paper, 2025). Any Mendelian diseases that affects growth and development of the skeleton. "Aside from the DYM pathogenic variant, variants of uncertain significance (VUS) were detected in WISP3, CSPP1, GNPTAB, and FLNB, genes known to be associated with skeletal dysplasias." (PMID 40428312, 2025).
GNPTAB also shares sentences with these, for which no sentence is quoted: tumor (8 papers); and-neck carcinoma (1); Bardet-Biedl syndrome (1); benign tumors (1); ciliopathies (1); Cirrhosis (1); ductal carcinoma in situ (1); epilepsy (1); Fabry disease (1); genetic disorders (1); glioma (1); hepatocellular carcinoma (1); infection (1); invasive ductal carcinoma (1); Joubert syndrome (1); Larsen syndrome (1); Leigh syndrome (1); Lipid storage disease (1); neurodegenerative disease (1); Papillary Thyroid Carcinomas (1); Parkinson disease (1); progressive pseudorheumatoid dysplasia (1); prostate carcinoma (1); Spastic paraplegia (1); spondyloepiphyseal dysplasia (1); thalassemia (1).